ACHE (acetylcholinesterase (Yt blood group))
Diseases named in the same sentence as ACHE in open-access papers (continued):
Sharing a sentence is not in itself a finding about the gene and the disease.
Alzheimer disease (continued). "A series of potent naphthalene-based AChE inhibitors were identified, synthesized, and evaluated for their in vitro and in vivo potentials against Alzheimer’s disease, in which one of these inhibitors is SF5." (PMID 35126145, 2021). "Galantamine is an inhibitor of the enzymatic activity of acetylcholinesterase (AChE), which degrades acetylcholine into choline and acetate, and a clinically-approved cholinergic drug for Alzheimer's disease." (PMID 33776997, 2021). "Several reports confirmed their ability to cross the blood–brain barrier and proved their potency in the treatment of Alzheimer’s disease via interfering with some potential targets, such as AChE and/or ERK2." (PMID 34208063, 2021). "Acetylcholine (ACh) is predominantly decomposed by AChE compared to BuChE, thus the inhibition of AChE to increase the level of ACh remains a promising strategy for the treatment of Alzheimer’s disease." (PMID 34770983, 2021). "Inhibition of AChE, the critical enzyme in the hydrolysis of acetylcholine, is the first-line therapy for Alzheimer’s diseases." (PMID 33129236, 2021). "AChE and BChE (cholinesterases) enzyme inhibitors are presently being utilized for the treatment/management of Alzheimer’s diseases (AD)." (PMID 34483902, 2021). "Ten acridones isolated from Atalantia monophylla were evaluated for effects on Alzheimer’s disease pathogenesis including antioxidant effects, acetylcholinesterase (AChE) inhibition, prevention of beta-amyloid (Aβ) aggregation and neuroprotection." (PMID 34577588, 2021). "Dapholosericin A, a tigliane diterpene from the EtOAc extract of D. holosericea, was discovered to be a moderate acetylcholinesterase (AChE) inhibitor at a concentration of 100 μM, which suggested its potential usage in the mediation of Alzheimer’s disease." (PMID 34771007, 2021). "In recent years, fungi have been recognized as producers of acetylcholinesterase (AChE) inhibitors, agents important for the prevention of Alzheimer’s disease (AD)." (PMID 33557141, 2021). "In Alzheimer's disease (AD), the enzyme acetylcholinesterase (AChE) co‐localizes with hyperphosphorylated tau (P‐tau) within neurofibrillary tangles." (PMID 32955735, 2021). "The reversible inhibitors of AChE (acetylcholinesterase enzyme) are being utilized generally in the treatment of neurodegenerative disorders, including Alzheimer’s disease (AD)." (PMID 34451622, 2021). "In Alzheimer’s disease (AD), two cholinesterases (ChEs) including acetylcholinesterase (AChE) and butyrylcholinesterase (BChE) are neurotransmitter degrading enzymes, while β-secretase (BACE-1) is involved with β-amyloid formation." (PMID 33924574, 2021). "The inhibition of AChE is used clinically to improve the quality of life in Alzheimer Disease (AD) patients, as well as in severe intestinal disorders." (PMID 34682308, 2021). "We evaluated the efficacy and safety of Souvenaid (a multinutrient supplement) in patients with mild Alzheimer’s disease (AD) in real clinical practice and assessed a potential synergistic effect of acetylcholinesterase (AChE) inhibitors." (PMID 33682712, 2021). "Some studies reported that SA has acetylcholinesterase (AChE) inhibition property which is beneficial for potential treatment of Alzheimer's disease (AD)." (PMID 33987539, 2021). "AChE has received considerable attention as a target of chemical intervention, particularly for therapeutic treatment of Alzheimer’s disease (AD)." (PMID 32825138, 2020). "(2014) also investigated the effect of R. graveolens on the inhibition of acetylcholinesterase (AChE) and butyrylcholinesterase (BuChE), which are considered as promising strategies in the treatment of Alzheimer’s disease (AD)." (PMID 32432948, 2020). "The inhibition of AChE and BChE is considered one of the possible therapeutic strategy against neurodegenerative disorders such as Alzheimer’s disease, senile dementia, and ataxia." (PMID 32825768, 2020).
Alzheimer disease (continued). "In Alzheimer’s disease (AD), AChE is overly active, and the consequential lower level of acetylcholine in the brain cause weakened neurotransmission." (PMID 33113950, 2020). "Food and Drug Administration (FDA) approved drugs donepezil, rivastigmine, tacrine and galantamine are AChE inhibitors and in the treatment of Alzheimer’s disease (AD) these drugs are currently prescribed." (PMID 33488178, 2020). "AChE inhibitors, used in the palliative treatment of Alzheimer's disease, have been investigated for their capability to protect central AChE16." (PMID 33024231, 2020). "Huperzine A isolated from H. serrata has a potent anti-acetylcholinesterase (AChE) activity, which has been approved in China as a drug to treat Alzheimer’s disease and is currently used as a supplement for preventing further memory degeneration in USA." (PMID 33211760, 2020). "As such, current symptomatic Alzheimer’s disease treatments, specifically AChE inhibitors donepezil and rivastigmine, act to remediate this cholinergic dysfunction through increasing the level of acetylcholine at the synaptic cleft." (PMID 32954291, 2020). "This common steroid is of interest as it has been reported to be a potent acetylcholinesterase (AChE) inhibitor for symptomatic treatment of Alzheimer’s disease." (PMID 32121043, 2020). "Nonetheless, due to the singularity in treating mild to moderate Alzheimer’s disease with AChE inhibitors and their side effects, make it necessary to find new anti-Alzheimer’s drugs." (PMID 33224224, 2020). "In early 1990s, when AChE inhibitors started to be developed for the palliative treatment of Alzheimer disease (AD), a related silyl compound, Zifrosilone was considered as a promising anti-AD symptomatic drug." (PMID 33260981, 2020). "An important approach to treat Alzheimer’s disease (AD) is to enhance the acetylcholine level in the brain by inhibition of AChE and cholinesterase inhibitors from plants, which are considered as promising candidates." (PMID 32575531, 2020). "Of all the candidates investigated recently, crinine-derivative 11-O-acetyl-9-O-demethylmaritidine and other-type Zephycandidine III are interesting targets for further anti-AChE investigation for Alzheimer’s disease." (PMID 33113950, 2020). "In line with the ChAT reduction in L1, hippocampal AChE levels have been reported to be significantly reduced in patients with mild cognitive impairment and early Alzheimer’s disease, displaying robust correlations to cognitive impairment." (PMID 32954291, 2020). "Recently, a single drug group, acetyl-cholinesterase (AChE) inhibitors have been used in the treatment of Alzheimer’s disease." (PMID 33224224, 2020). "AChE is the key enzyme for the termination of neurotransmission in cholinergic pathways, and AChE inhibition is an effective approach for the symptomatic treatment for Alzheimer’s disease (AD)." (PMID 33143384, 2020). "Acetylcholinesterase (AChE, E.C.3.1.1.7) enzyme plays a vital role in the treatment of Alzheimer’s disease (AD)." (PMID 33488212, 2020). "The inhibition of both AChE and BChE improves cognitive function and minimizes the accumulation of β-amyloid and is a viable strategy for treating Alzheimer’s disease." (PMID 32695454, 2020). "Currently, in terms of commercial success, galantamine, widely occurring in the Amaryllidaceae plants, has been approved as an AChE inhibitor by the United States Food and Drug Administration to treat the symptoms of Alzheimer’s disease (AD)." (PMID 33113950, 2020). "Inhibition of acetylcholinesterase (AChE) and butyrylcholinesterase (BChE) has great potential in the treatment of Alzheimer’s disease and special focus has been directed to these targets." (PMID 33352776, 2020). "In summary, nine coumarins from Toddalia asiatica root were evaluated for activities related to the pathogenesis of Alzheimer’s disease, including anti-AChE function, AChE- and self-induced Aβ aggregation." (PMID 32370238, 2020).
Alzheimer disease (continued). "Tacrine, an AChE inhibitor, was one of the first medicinal materials for alleviating and treating Alzheimer’s disease to be consumed widely." (PMID 32679768, 2020). "To date, the only nAChR PAM commercially available for human use is the acetylcholinesterase (AChE) inhibitor galantamine, approved by the Food and Drug Administration for the treatment of mild to moderate Alzheimer’s disease." (PMID 31686175, 2020). "Acetylcholinesterase (AChE) inhibition and antioxidants are two common strategies for the treatment in the early stage of Alzheimer's Disease (AD)." (PMID 32148536, 2020). "Alzheimer's disease (AD) is a prevalent neurodegenerative disorder with multifactorial causes, of which systemic inflammation may play a key role to promote neurodegeneration, and acetylcholinesterase (AChE) is a target protein to induce cholinergic transmission." (PMID 32523534, 2020). "Anatomical studies have found that AChE protein expression in the brain of Alzheimer’s disease (AD) patients is elevated." (PMID 31349561, 2019). "A novelty in terms of evaluation of hop cone biofunctionality is the determination of a marker related to the activity of AChE and BChE inhibitors used in the treatment of neurodegenerative diseases, especially in Alzheimer’s disease." (PMID 31248112, 2019). "One of these drugs, the centrally acting AChE inhibitor galantamine is in clinical use for counteracting cognitive impairment in Alzheimer’s disease." (PMID 31024226, 2019). "AChE catalyzes the breakdown of acetylcholine and inhibition of AChE is a major target for Alzheimer’s disease." (PMID 31046739, 2019). "Galantamine is a centrally acting AChE inhibitor that has been FDA approved to treat the cognitive impairment in patients with Alzheimer’s disease in the United States for more than a decade." (PMID 31024226, 2019). "The majority of derivatives inhibit AChE more efficiently than BuChE and are comparable or superior to rivastigmine—an established cholinesterases inhibitor used in the treatment of Alzheimer’s disease." (PMID 31694272, 2019). "In recent decades, Acetylcholinesterase (AChE) has become a major interest in Alzheimer’s disease (AD) research." (PMID 30785927, 2019). "The result of this study after the comparison of the salivary samples of the healthy subjects and those diagnosed with Alzheimer's disease concluded the fact that AChE and PChE levels were increased in saliva samples of patients with Alzheimer's disease." (PMID 30906485, 2019). "Nevertheless, a decrease in the level of ACh in the brain and an increase in the level of AChE in the hippocampus are documented in Alzheimer’s disease." (PMID 31068802, 2019). "The development of novel inhibitors of acetylcholinesterase (AChE) and butyrylcholinesterase (BuChE) represents a viable approach to alleviate Alzheimer’s disease." (PMID 31694272, 2019). "Acetylcholinesterase (AChE) is the main target of the currently marketed drugs against Alzheimer’s Disease (AD)." (PMID 31370232, 2019). "The acridine derivative tacrine was the first AChE inhibitor developed to improve the cognitive performance of Alzheimer’s disease, and ranitidine is an inhibitor of histamine type 2 (H2) receptors, which is widely used to reduce gastric acid production." (PMID 31191210, 2019). "Effect of Lampranthus coccineus, Malephora lutea extracts and Rivastigmine drug on brain acetylcholinestrase (AChE) in Alzheimer's disease induced rats." (PMID 31693694, 2019). "Currently, inhibitors of acetylcholinesterase (AChE) have been used for treatment of Alzheimer’s disease." (PMID 31861353, 2019). "It has been described that in Alzheimer’s disease, AChE expression is substantially altered, and its activity is decreased in most brain regions." (PMID 31295866, 2019). "Alzheimer’s disease (AD) is a major neurodegenerative disorder characterized by an increase in acetylcholinesterase (AChE) levels around β-amyloid plaques and neurofibrillary tangles." (PMID 31216636, 2019).
Alzheimer disease (continued). "We then tested their AChE inhibit activities to search for natural material in preventing Alzheimer’s Disease (AD)." (PMID 31597363, 2019). "The aim of this study was to evaluate the pharmacological effect of Calligonum polygonoides against Krait snake’s venom AChE and also to study the potential of C. polygonoides in treatment of Alzheimer’s disease." (PMID 30186576, 2018). "In November 2006, NICE revised their guidance so that the use of AChE inhibitors was restricted to patients with moderate Alzheimer’s disease; this was defined as patients scoring between 10 and 20 points on the MMSE." (PMID 29843807, 2018). "AChE inhibitors for the treatment of Alzheimer’s disease became available generically from 2012, whereas NMDA receptor antagonists became available generically from 2014." (PMID 29843807, 2018). "AChE inhibitors (AChEIs) are the main drugs currently in use for treatment of Alzheimer’s disease (AD), the most common form of dementia." (PMID 29651876, 2018). "It is noteworthy that some of these compounds are formally derived, by quaternization, from centrally-acting AChE inhibitors that are being used for treatment of Alzheimer’s disease, such as donepezil." (PMID 29534488, 2018). "Donepezil and rivastigmine are considered to be the most effective and most commonly used AChE inhibitors during Alzheimer's disease pharmacotherapy." (PMID 30577562, 2018). "The inhibitions of AChE and BChE activities have been established as an effective strategy for treatment of Alzheimer's disease (Howes, Perry, & Houghton, 2003)." (PMID 30349669, 2018). "Several previous studies have shown that some natural products have therapeutic effects on Alzheimer’s disease (AD), the representative neurodegenerative disorder, by repressing the key regulators including acetylcholine protease (AChE) and tau51–53." (PMID 29849106, 2018). "The original NICE guidance, issued in 2001, on the use of drugs to treat Alzheimer’s disease recommended that the three AChE inhibitors should be used for all patients scoring 12 or above on the MMSE until the drugs were deemed no longer effective." (PMID 29843807, 2018). "Drugs as rivastigmine (used as positive control in our study), galantamine and huperzine A (active principles isolated from medicinal plants) are AChE inhibitors employed in the treatment of Alzheimer’s disease." (PMID 29866157, 2018). "Acetyl-cholinesterase enzyme (AChE) is a known target for identifying potential inhibitors against Alzheimer diseases (AD).Therefore, it is of interest to screen AChE with the CNS-BBB database." (PMID 30310249, 2018). "The proportion of patients with probable Alzheimer’s disease receiving their first prescription for an AChE inhibitor increased throughout the study period." (PMID 29843807, 2018). "The objective of this study was to evaluate pharmacological effect of Calligonum polygonoides against Krait snake’s venom acetylcholinesterase (AChE) and to extent it for the treatment of Alzheimer’s disease." (PMID 30186576, 2018). "AChE inhibitors are used clinically on the treatment of Alzheimer’s disease, because they increase the availability of acetylcholine present in cholinergic synapses, enhancing the cholinergic functions." (PMID 29866157, 2018). "Various reports have shown that phthalimide derivatives are potent inhibitors of AChE, a key enzyme involved in the deterioration of the cholinergic system during the development of Alzheimer’s disease." (PMID 29938351, 2018). "The first trend change for the proportion of patients with probable Alzheimer’s disease receiving their first prescription for an AChE inhibitor occurred in October 2012 (95% CI, September 2011 to April 2013, p = 0.816)." (PMID 29843807, 2018). "C. polygonoides extract can be considered as a therapeutic agent to cure Alzheimer’s disease via inhibition of AChE activity to increase the level of acetylcholine in the body system." (PMID 30186576, 2018).
Alzheimer disease (continued). "AChE inhibitors currently approved as drugs for the treatment of Alzheimer's disease are donepezil, rivastigmine, galantamine, and tacrine." (PMID 29632858, 2018). "The protective effects of TQ against Alzheimer’s disease are most likely due to its AChE inhibitory and antioxidant properties." (PMID 29881705, 2018). "According to cholinergic neurotransmission, acetylcholinesterase (AChE) inhibition would increase the levels of acetylcholine in the brain, thus improving cholinergic synapses in Alzheimer’s disease (AD) patients." (PMID 30217053, 2018). "The use of AChE inhibitors in the therapy of Alzheimer’s disease (AD) has since then ensured a continuous interest in the search for new molecules acting as AChE/BChE inhibitors." (PMID 29382051, 2018). "Donepezil and tacrine, which are AChE inhibitors and have been used as therapeutic agents for Alzheimer’s disease (AD), show a relatively high distribution in the brain." (PMID 28490336, 2017). "Context: Antiacetylcholinesterase (AChE) drugs have been a main therapeutic treatment for Alzheimer’s disease because increased AChE levels play a key role in reducing neurotransmission." (PMID 29115888, 2017). "Here, we demonstrated that an ethanol extract of P. chinense had a potent effect on Alzheimer’s disease-related in vitro bioevents, such as AChE activation, antioxidation, and the protection against neuronal cell damage." (PMID 28574473, 2017). "It has been suggested that fucoxanthin exhibited great therapeutic efficacy in Alzheimer’s disease by inhibiting acetylcholinesterase (AChE) and increasing brain-derived neurotrophic factor (BDNF) expression." (PMID 28429775, 2017). "AChE inhibitors (AChEIs) have medical applications and are particularly important for the symptomatic treatment of Alzheimer’s disease." (PMID 29088082, 2017). "AChE and BuChE are druggable targets for the discovery of anti-Alzheimer’s disease drugs, while dual-inhibition of these two targets seems to be more effective." (PMID 28718678, 2017). "Patients suffering from Alzheimer’s disease show a marked reduction in AChE activity and the use of drugs boosting cholinergic function can ameliorate memory deficits." (PMID 28443003, 2017). "Acetylcholinesterase (AChE) inhibitors are widely used for the symptomatic treatment of Alzheimer’s disease (AD) and other dementias." (PMID 29108348, 2017). "Previous reports state the inhibitory activity of water-alcoholic extracts of different Hypericum species on acetylcholinesterase (AChE), suggesting the potential beneficial effects in patients suffering from Alzheimer's disease (AD)." (PMID 29362586, 2017). "It is thus assumed that HupA has a longer residence time than other anti-AChE drugs that have been used for the treatment of Alzheimer’s disease." (PMID 28796192, 2017). "Multifunctional carbamate-type acetylcholinesterase (AChE) inhibitors with anti-amyloidogenic properties like phenserine are potential therapeutic agents for Alzheimer’s disease (AD)." (PMID 28274151, 2017). "This is the first study showing the neuroprotective potential of troxerutin against Aβ 1-42-induced Alzheimer's disease possibly through its anti-apoptotic, antioxidant, and AChE inhibitory effects in the hippocampus." (PMID 29285004, 2017). "In summary, a series of hesperetin derivativeswere designed and synthesized on the basis of the structural characteristics of the AChE dual-site inhibitors as multifunctional anti-Alzheimer’s Disease agent." (PMID 28672874, 2017). "Virgin coconut oil (VCO) has been the subject of several studies which have aimed to alleviate Alzheimer’s disease (AD) pathology, focusing on in vitro antioxidant and acetylcholinesterase (AChE) inhibitory activities." (PMID 28536360, 2017).